IL10 (interleukin 10)
Diseases named in the same sentence as IL10 in open-access papers (continued):
Sharing a sentence is not in itself a finding about the gene and the disease.
Salmonella Infections (continued). "IL-10 levels are elevated in susceptible strains of mice suggesting that those strains producing IL-10 at high levels cannot adequately control Salmonella infection." (PMID 27149619, 2016). "IL-10 has been shown to be important in the pathogenesis of Salmonella infection and regulation of subsequent host immune responses." (PMID 27149619, 2016). "Anti-inflammatory IL10, which plays a role in controlling the inflammatory response during Salmonella infection was also up-regulated (FC = 72.4)." (PMID 25752829, 2015). "In addition, we measured the levels of additional cytokines (IL-10 and TNF-α) associated with Salmonella infections." (PMID 34484221, 2021). "The majority of interleukins secreted by macrophages and lymphocytes contributes antimicrobial defense or protective effects, but IL-8 and IL-10 may promote systemic Salmonella infection." (PMID 34943999, 2021). "Salmonella infection increase IL-10 mRNA content in the cecal tonsils." (PMID 31600299, 2019). "Interestingly, a subset of plasmablasts, called regulatory plasmablasts, has been reported to express both Blimp-1 and IL-10 during Salmonella infection and in EAE." (PMID 31474988, 2019). "It has been reported that B cells produce IL-10 in response to Salmonella infection." (PMID 30103648, 2018). "Interestingly, B cell IL10 production also attenuates aspects of innate and adaptive immunity in a salmonella infection model, and IRF4HiCD138Hi PCs have been identified as a potent source of IL10." (PMID 28767707, 2017). "IL-10 is increased via a SPI2 dependent mechanism during Salmonella infection, and may inhibit ROS and RNS in macrophages." (PMID 23922794, 2013). "Although we focused our analysis on IFN-γ, IL-6 and IL-10 may also be important mediators of the mucosal responses to Salmonella infection." (PMID 22624013, 2012). "During Salmonella infection, mice with a targeted deletion of MyD88 in B-cells exhibited an accumulation of neutrophils in the spleen, an effect that likely depends on Bregs-mediated IL-10 production." (PMID 23308074, 2012). "However, the anti-CD3/CD28 stimulated IFN-γ and IL-10 response was significantly attenuated following Salmonella infection in the B. infantis-fed animals." (PMID 18670628, 2008). "IL-6 and IL-10 gene expression are also significantly increased in infected p19−/− mice, and these cytokines may contribute to host defense and mucosal tissue injury against Salmonella infection in p19−/−." (PMID 22624013, 2012). "Our data show a variation in the IL10 induction effect of viable and heat-killed KUNN19-2 among different strains of Salmonella infection." (PMID 40076451, 2025). "In response to Salmonella infection, elevated levels of pro- and anti-inflammatory cytokines, including IFN-γ, TNF-α, IL-17, and IL-10 have been detected in the placenta, amniotic fluid, and maternal serum." (PMID 40709995, 2025). "During Salmonella infection and EAE, IL-35- and IL-10-producing B cells were the main source of B-cell-derived IL-35 and IL-1026." (PMID 32764544, 2020). "Regarding infectious diseases, Salmonella infection sufficiently enhances LILRB4 expression on DCs and monocytes and its activation results in increased levels of IL-10 production." (PMID 31849951, 2019). "For example, B-cell derived IL10 suppressed pathogen-specific CD4+ T cell, natural killer, and neutrophil responses which correlated with decreased survival in a salmonella infection model." (PMID 28767707, 2017). "Even though DKO mice succumbed to Salmonella infection earlier than MyD88−/− mice, both strains had low serum IFN-γ and elevated IL-10." (PMID 26441965, 2015). "Based on our previous observations, we were interested whether blocking of IL-10 could rescue the production of IFNγ in CD4+ T cells and therefore be beneficial for the control of the Salmonella infection in conditions of iron overload in Tim3−/− mice." (PMID 40939292, 2025).
Salmonella Infections (continued). "Moreover, B cell expression of TLR2/4 or their downstream mediator MyD88 is required for an optimal IL-10 production upon LPS stimulation and to achieve in vivo suppression by IL-10+ Bregs in the EAE and Salmonella infection models." (PMID 33995344, 2021). "We also measured the systemic levels of two markers, IL-10 and IFN-γ, which may contribute to a better understanding of autoantibody induction during and after Salmonella infection." (PMID 31277323, 2019). "In mouse peritoneal MΦs, Salmonella infection up-regulated the expression of both of M1 MΦ markers (CCR7 and CD86), M2 MΦ marker (CD163 and CD206) and induced the secretion of M1 MΦ marker TNF-α and M2 MΦ marker IL-10 in ascitic fluid significantly." (PMID 30271755, 2018). "Overall, our data revealed that synergistic effects of CD40 and MyD88 do not influence host survival to Salmonella infection or serum levels of IFN-γ or IL-10." (PMID 26441965, 2015). "Another study showed that probiotic Lactobacillus efficiently reduced Salmonella infection and gut inflammation by increasing the levels of propionic acid and mucin-2, as well as changing the level of tumor necrosis factor-alpha (TNF-a), interleukin-10 (IL-10) and myeloperoxidase (MPO) in mice." (PMID 32150574, 2020). "In the Salmonella infection model, the quantity of dietary iron did not affect the expression of TIM-3, IFNγ, or IL-10 on CD8+ T cells." (PMID 40939292, 2025). "Collectively, these data show that GSK3 kinase activity is required specifically for SteE- but not IL-10-mediated Y705-STAT3 phosphorylation and upregulation of the M2 marker IL-4Rα during Salmonella infection." (PMID 31862381, 2020). "Overall, our data using mice with a single or double deficiency in MyD88 and CD40 revealed that synergistic effects of CD40 and MyD88 do not influence host survival to Salmonella infection, CFUs in infected tissues or serum levels of IFN-γ or IL-10." (PMID 26441965, 2015).
campylobacteriosis (46 papers, 2011 to 2025). Infections with bacteria of the genus campylobacter. "When activated charcoal was used for the treatment of the C. jejuni infected human gut microbiota associated (hma) IL-10−/− mice, the campylobacteriosis symptoms and pro-inflammatory signaling were significantly reduced." (PMID 40395728, 2025). "Following oral C. jejuni infection, human gut microbiota associated IL-10−/− mice were shown not only to carry the pathogen in their intestines at high loads but also to present with key symptoms of acute campylobacteriosis like secondary abiotic mice do." (PMID 38343716, 2024). "In particular, the LOS sensitized secondary abiotic IL-10 deficient mice were successfully used for groundbreaking studies for a better molecular understanding of immunopathogenesis of campylobacteriosis." (PMID 32231139, 2020). "After defining the genotype and reversible motility phenotype of 11168wt, 11168mot-, and 11168mot+, we sought to assess the ability of these variants to colonize the C57BL/6 IL-10–/– mouse model of campylobacteriosis." (PMID 33240235, 2020). "We found that specific pathogen free (SPF) Il10-/- mice resisted against C. jejuni 81–176 induced colitis, while the mice were susceptible to campylobacteriosis after treated with antibiotic clindamycin which kills bile acid metabolizing bacteria." (PMID 31276498, 2019). "In the past few years, secondary abiotic as well as conventional NOD2 deficient IL-10−/− (NOD2−/− IL-10−/−) mice were used to unravel the role of the innate immune receptor nucleotide-oligonucleotide-domain 2 (NOD2) during campylobacteriosis and clearance of C. jejuni infection." (PMID 32231139, 2020). "By using germ-free IL-10 and Rag2 double deficient mice the authors confirmed the hypothesis that innate immune cells are the main cellular compartment responsible for campylobacteriosis." (PMID 32231139, 2020). "We and others have applied microbiota-depleted interleukin-10-deficient (IL-10−/−) mice, for instance, that develop C. jejuni-induced intestinal inflammation resembling clinical and immunopathological key features of human campylobacteriosis." (PMID 33003421, 2020). "This might indicate that the observed symptoms induced by A. butzleri in our gnotobiotic IL-10 deficient mice mimic arcobacteriosis in humans, which is thought to cause milder disease symptoms as compared to human campylobacteriosis." (PMID 26483849, 2015). "Most importantly, the major role of LOS-induced intestinal immunopathology during campylobacteriosis was independently confirmed in elegant infection experiments with microbiota depleted SIGGR−/− mice developing campylobacteriosis similar to secondary abiotic IL-10 deficient mice." (PMID 32076081, 2020). "Vitamin C administration to the secondary abiotic IL-10−/− mice starting 4 days prior C. jejuni infection alleviated clinical symptoms of campylobacteriosis and reduced pathogen-induced apoptosis rates in colonic epithelia." (PMID 40395728, 2025). "Our recent study underscored the suitability of the hma IL-10−/− mouse model to test the disease-alleviating effects of defined molecules such as carvacrol, for instance, during acute campylobacteriosis." (PMID 38397378, 2024). "The used hma IL-10−/− mice constitute a valuable acute campylobacteriosis model to dissect the interplay between distinct prophylactically or therapeutically applied compounds, the enteropathogen, host immunity, and human gut commensals in vivo." (PMID 38397378, 2024). "Mice with deficiencies in IL-10, single IgG IL-1 Related Receptor (SIGIRR) and mice subjected to zinc depletion developed campylobacteriosis symptoms upon C. jejuni infection." (PMID 36979344, 2023). "In the actual study, we used the SAB IL-10−/− mouse model to assess the anti-pathogenic and/or immune-modulatory effects of LEM-EO and COR-EO in acute campylobacteriosis upon prophylactic application." (PMID 37065112, 2023).
campylobacteriosis (continued). "Given that interleukin-10 (IL-10) is required for LOS resistance, researchers use IL-10−/− mice following gut microbiota depletion as a practical and reliable model for campylobacteriosis caused by C. jejuni-induced pro-inflammatory immune responses." (PMID 36296229, 2022). "Within a week after oral C. jejuni infection, microbiota-depleted IL-10−/− mice display LOS-driven human campylobacteriosis." (PMID 36671455, 2022). "All these multifaceted beneficial effects of clove EO prompted us to evaluate this natural product as potential treatment option of campylobacteriosis in a preclinical setting for the first time by using C. jejuni infected microbiota-depleted IL-10−/− mice." (PMID 33807493, 2021). "In our present mouse model of campylobacteriosis, infected secondary abiotic IL-10−/− mice suffered from acute enterocolitis within one week after infection, as indicated by bloody diarrhea and wasting." (PMID 33935732, 2021). "A key mechanism of C. jejuni-induced immunopathology during acute campylobacteriosis in infected secondary abiotic IL-10-/- mice is the induction of the TLR-4 dependent signaling cascade by bacterial cell wall-derived LOS." (PMID 34070612, 2021). "Il10−/− mouse infection model has recently been successfully developed to mimic human campylobacteriosis in various labs." (PMID 33257743, 2020). "In our preclinical intervention study, we assessed potential anti-pathogenic and immunomodulatory effects of ascorbate in C. jejuni-infected secondary abiotic IL-10−/− mice developing acute campylobacteriosis similar to humans." (PMID 32076081, 2020). "Nevertheless, we expanded our intestinal inflammatory survey of campylobacteriosis induced in secondary abiotic IL-10−/− mice to the small intestines." (PMID 31921356, 2020). "Our group has established a clinical C. jejuni infection model based on abiotic IL-10−/− mice mimicking key features of human campylobacteriosis." (PMID 31131028, 2019). "Our long-term goal is to use microbiome to reduce C. jejuni transmission in chickens and to attenuate transmitted campylobacteriosis using mouse Il10-/- model." (PMID 31276498, 2019). "We used the gnotobiotic IL-10−/− mouse model to study campylobacteriosis following peroral infection with the C. jejuni wild-type (WT) strain NCTC11168 and the isogenic, non-polar NCTC11168ΔhtrA deletion mutant." (PMID 24959425, 2014). "We demonstrate that CiaD is necessary for the development of disease and colon inflammatory lesions in vivo using the IL-10 KO mouse model for campylobacteriosis." (PMID 24144181, 2013). "Together, these data indicate that CiaD is necessary for the development of disease in the IL-10-/- mouse model of campylobacteriosis." (PMID 24144181, 2013). "Gnotobiotic IL-10−/− mice develop acute enterocolitis following C. jejuni infection mimicking severe episodes of human campylobacteriosis and are thus well suited to further dissect mechanisms underlying Campylobacter infections in vivo." (PMID 22808254, 2012). "We here demonstrate that following C. jejuni infection gnotobiotic IL-10−/− mice develop acute enterocolitis as in human campylobacteriosis." (PMID 22808254, 2012). "In previous work we showed that the virulence of C. jejuni NCTC11168 increased after serial passage through a C57BL/6 IL-10-/- mouse model of campylobacteriosis." (PMID 21283682, 2011). "In addition, activated T cells can produce the cytokines IL-4 and IL-10, which serve as anti-inflammatory factors that counteract severe courses of campylobacteriosis by dampening the immune responses." (PMID 40395728, 2025). "Therefore, the preclinical intervention study using secondary abiotic IL-10−/− mice as a C. jejuni infection model provides a new promising approach for prophylaxis and treatment of acute campylobacteriosis by vitamin C administration." (PMID 40395728, 2025).
campylobacteriosis (continued). "Thus, treatment of microbiota-depleted and C. jejuni-infected IL-10−/− mice with essential oils of either cardamom, clove, garlic or cumin alleviated clinical signs of acute campylobacteriosis in all cases." (PMID 40395728, 2025). "The hma IL-10−/− mice were further infected with C. jejuni and treated with carvacrol, which eventually dampened intestinal and extra-intestinal inflammatory responses during acute campylobacteriosis." (PMID 40395728, 2025). "In our present preclinical placebo-controlled intervention study, we tested the disease-mitigating, anti-pathogenic, anti-inflammatory, anti-oxidant and anti-apoptotic effects of oral menthol in acute experimental campylobacteriosis employing hma IL-10−/− mice." (PMID 38540710, 2024). "In our previous in vivo study employing a different murine campylobacteriosis model, we found that oral menthol of the same concentration therapeutically given to secondary abiotic IL-10−/− mice from day 2 until day 6 p.i. resulted in an improved clinical outcome." (PMID 38540710, 2024). "The here observed C. jejuni induced fecal microbiota shifts could be confirmed by our previous studies showing increased colonic enterobacterial counts but decreased obligate anaerobic bacterial numbers during acute campylobacteriosis in hma IL-10−/− mice." (PMID 38397378, 2024). "In consequence, secondary abiotic IL-10−/− mice can be colonized by the enteropathogen and also display C. jejuni-induced acute enterocolitis within a week post infection (p.i.)mimicking key features of severe and invasive human campylobacteriosis." (PMID 38343716, 2024). "Hence, combination organic acid treatment of C. jejuni infected IL-10–/– mice improved the overall clinical outcome of acute campylobacteriosis and particularly alleviated diarrheal symptoms in infected mice." (PMID 37007531, 2023). "Therefore, secondary abiotic IL-10−/− mice display C. jejuni-induced acute enterocolitis within a week p.i. and display severe episodes of human campylobacteriosis." (PMID 36830689, 2023). "In conclusion, the results of our preclinical placebo-controlled intervention study provide evidence that the therapeutic application of carvacrol dampens intestinal and extra-intestinal inflammatory responses during acute campylobacteriosis in IL-10−/− mice harboring a human gut microbiota." (PMID 36830689, 2023). "The described immune-modulatory and antibacterial effects of tormentil, raspberry leaves, loosestrife, and menthol prompted us to test the respective compounds alone and all four in combination against acute campylobacteriosis, applying the microbiota-depleted IL-10−/− mouse model." (PMID 37896170, 2023). "Interestingly, mTOR is the cellular target for the immune suppressor rapamycin (sirolimus) that has been shown to potently ameliorate acute campylobacteriosis in infected IL-10−/− mice." (PMID 36830689, 2023). "Evidence that VD has a protective effect on the intestinal epithelium in campylobacteriosis came from our preclinical intervention study in IL-10−/− mice, which demonstrated that peroral administration of cholecalciferol reduced the severity of inflammation during acute C. jejuni infection." (PMID 34445577, 2021). "Thus, the microbiota-depleted IL-10−/− mouse model resembles main immunopathological features of acute LOS-driven campylobacteriosis in humans." (PMID 34209438, 2021). "It was recently shown that the abiotic IL-10−/− mice (gut microbiota depleted by broad-spectrum antibiotic treatment) are effectively colonized by C. jejuni upon peroral infection and develop key features of acute human Campylobacteriosis." (PMID 31936044, 2020). "In the present pre-clinical intervention study we therefore applied a well-established clinical C. jejuni infection model of acute campylobacteriosis by using secondary abiotic IL-10−/− mice which display the clinical hallmarks of severe campylobacteriosis seen in human patients." (PMID 31921356, 2020).